KIF3B (kinesin family member 3B)
Description:
Microtubule-based molecular motor that transport intracellular cargos, such as vesicles, organelles and protein complexes. Uses ATP hydrolysis to generate force to bind and move along the microtubule (By similarity). Plays a role in cilia formation. Involved in photoreceptor integrity and opsin trafficking in rod photoreceptors. Transports vesicles containing N-methyl-D-aspartate (NMDA) receptor subunit GRIN2A into neuronal dendrites (By similarity).
Synonyms: KIAA0359; FLA8; KLP-11; HH0048; OTSC12; RP89
Tractability: Small molecule: a structure with a bound ligand is known; it has a binding pocket of medium quality. PROTAC: ubiquitination databases record sites on it; its protein half-life has been measured.
Target class: Other cytosolic protein
Gene: Protein-coding gene on chromosome 20 (32,277,651 to 32,335,011, forward strand). Ensembl gene ENSG00000101350.
Subcellular location: Cytoplasm, cytoskeleton; Cell projection, cilium; Cell projection, dendritic spine
Subcellular location (Human Protein Atlas): Flagellar centriole; Nucleoplasm; Primary cilium tip; Connecting piece; Cytosol
Pathways (Reactome):
Vesicle-mediated transport: COPI-dependent Golgi-to-ER retrograde traffic; Translocation of SLC2A4 (GLUT4) to the plasma membrane
Hemostasis: Kinesins
Immune System: MHC class II antigen presentation
Organelle biogenesis and maintenance: Intraflagellar transport
Gene Ontology:
Molecular function: protein binding; small GTPase binding; microtubule motor activity; plus-end-directed microtubule motor activity; ATP binding; intraciliary transport particle B binding; microtubule binding
Biological process: cilium assembly; intraciliary transport; mitotic spindle assembly; opsin transport; anterograde axonal transport; anterograde dendritic transport of neurotransmitter receptor complex; determination of left/right symmetry; mitotic centrosome separation; mitotic spindle organization; plus-end-directed vesicle transport along microtubule; axo-dendritic transport; microtubule-based movement; vesicle-mediated transport
Cellular component: extracellular exosome; kinesin II complex; membrane; microtubule cytoskeleton; centrosome; ciliary tip; cilium; cytosol; dendrite; kinesin complex; plus-end kinesin complex; spindle microtubule; axon cytoplasm; cytoplasm; cytoskeleton; dendrite cytoplasm; dendritic spine; glutamatergic synapse; postsynapse
Genetic constraint (gnomAD): Loss-of-function variants: 32 observed, 63.28 expected, observed/expected ratio (o/e) 0.51, 90% interval 0.38 to 0.68. The upper end of that interval is the gene's LOEUF score, 0.68, which puts it in group 2 of 6, group 1 being the genes least tolerant of losing a copy. Missense variants: 584 observed, 890.8 expected, observed/expected ratio (o/e) 0.66, 90% interval 0.61 to 0.7. Synonymous variants: 302 observed, 337.24 expected, observed/expected ratio (o/e) 0.9, 90% interval 0.81 to 0.99.
Homologues: Orthologues: chimpanzee KIF3B (100% identical), macaque KIF3B (99% identical), dog KIF3B (99% identical), rabbit KIF3B (99% identical), pig KIF3B (99% identical), guinea pig KIF3B (98% identical), mouse Kif3b (98% identical), rat Kif3b (98% identical), tropical clawed frog kif3b (86% identical), zebrafish kif3b (82% identical), Caenorhabditis elegans klp-11 (50% identical), Drosophila melanogaster Klp68D (47% identical). Paralogues in human: KIF3C (65% identical), KIF3A (47% identical), KIF17 (43% identical), KIF13B (31% identical), KIF1B (30% identical), KIF1A (30% identical), KIF13A (29% identical), KIF11 (29% identical), KIF16B (28% identical), KIF21B (28% identical), KIF21A (28% identical), KIF1C (28% identical), and 29 more.
Diseases named in the same sentence as KIF3B in open-access papers:
KIF3B is named in the same sentence as 43 diseases in open-access papers, as found by Europe PMC text mining. Sharing a sentence is not in itself a finding about the gene and the disease. The quoted sentences say what the papers report.
breast carcinoma (6 papers, 2016 to 2024). "In this study, we studied the expression level of KIF3B in breast cancer tissues and metastatic lymph nodes and its association with cancer progression." (PMID 33542902, 2020). "Collectively, our results provided support for the first time that KIF3B was highly expressed in breast cancer, and the high level expression was closely associated with lymph node metastasis and tumor recurrence." (PMID 33542902, 2020). "For example, KIF3A and KIF3B have been reported to be implicated in oncogenesis and metastasis of breast cancer and renal carcinoma." (PMID 27128470, 2016). "We also discovered that silencing of KIF3B may cause morphological changes in the breast cancer cells." (PMID 33542902, 2020). "Association between KIF3B in breast cancer and patient characteristics." (PMID 33542902, 2020). "And the increased expression of KIF3B was correlated with lymph node metastasis and tumor recurrence, suggesting a significant association of high KIF3B expression with tumor growth and metastasis of breast cancer." (PMID 33542902, 2020). "KIF3B has been identified as a potential therapeutic target for various cancers, including breast cancer, pancreatic cancer, cervical cancer, and oral squamous cell carcinoma." (PMID 38666838, 2024). "The study has indicated that the activation of Wnt/β-catenin mediated by KIF3B directly promote the growth, invasion, and epithelial-mesenchymal transition of breast cancer cells." (PMID 34422048, 2021). "Taken together, our results revealed that KIF3B is up-regulated in breast cancer which is potentially involved in breast cancer progression and metastasis." (PMID 33542902, 2020). "Our data firstly provided evidence that KIF3B expression was significantly increased at both the mRNA and protein levels in breast cancer tissues compared with the corresponding adjacent tissues." (PMID 33542902, 2020). "Real time RT-PCR and western blot assays were performed to examine the expression level of KIF3B in breast cancer tissues and nine pairs of fresh tissues." (PMID 33542902, 2020). "The objective of this study was to explore the expression, regulation, and mechanism of KIF3B in 103 cases of breast cancer tissues, 35 metastatic lymph nodes and breast cancer cell lines, including MDA-MB-231, MDA-MB-453, T47D, and MCF-7." (PMID 33542902, 2020). "In this study, we firstly revealed that KIF3B is a potent activator of Wnt signaling in human breast cancer." (PMID 33542902, 2020). "We further detected KIF3B expression by immunohistochemistry and confirmed that KIF3B expression was higher in breast cancer than in corresponding adjacent tissues (P < 0.01)." (PMID 33542902, 2020). "The expression of KIF3B is increased in breast cancer N0–N2 status, but decreased in N3 status (P < 0.01)." (PMID 33542902, 2020). "All these data indicated that deletion of KIF3B inhibited proliferation and invasion of breast cancer cells probably by regulating the Wnt/β-catenin signaling pathway." (PMID 33542902, 2020). "We evaluated KIF3B expression and prognostic value in breast cancer patients by using the UALCAN database." (PMID 33542902, 2020). "We observed that KIF3B expression increased in breast cancer stages 1–3 compared to normal samples (P < 0.01)." (PMID 33542902, 2020). "The results showed that both the mRNA (P < 0.01) and protein levels (P < 0.01) of KIF3B in the tumor tissues were markedly higher than that of the corresponding adjacent tissues, demonstrating that KIF3B was up-regulated in breast cancer." (PMID 33542902, 2020). "Furthermore, breast cancer patients with high-expression of KIF3B (n = 271) displayed worse survival compared to the patients with low/medium-expression of KIF3B (n = 810) (P < 0.01)." (PMID 33542902, 2020).
breast carcinoma (continued). "The results showed that KIF3B expression was up-regulated in breast cancer tissues and cell lines, and the expression level was correlated with tumor recurrence and lymph node metastasis, while knockdown of KIF3B suppressed cell proliferation, migration, and invasion both in vivo and in vitro." (PMID 33542902, 2020). "In addition, KIF3B depletion inhibited epithelial mesenchymal transition (EMT) in breast cancer cells." (PMID 33542902, 2020). "In addition, UALCAN analysis showed that KIF3B expression in breast cancer is increased, and the high expression of KIF3B in breast cancer is associated with poor prognosis." (PMID 33542902, 2020). "Collectively, these results indicate that KIF3B silencing could significantly suppress breast cancer metastasis both in vivo and in vitro." (PMID 33542902, 2020). "In addition, the expression level of E-cadherin was up-regulated and expressions of Vimentin, MMP-2, MMP-9, Slug and Snail were reduced in the xenografts in the KIF3B-shRNA group compared with the control group by IHC staining, which were consistent with the results in breast cancer cell lines." (PMID 33542902, 2020). "In addition, KIF3B knockdown might repress proliferation, migration, and invasion through regulating Wnt/β-catenin signaling and EMT in breast cancer cells, suggesting that KIF3B plays a key regulatory role in cell proliferation and metastasis in breast cancer." (PMID 33542902, 2020). "This phenotype was also observed in KIF3B mutant human HT1080 fibrosarcoma and MDA231 breast cancer cells." (PMID 29904055, 2018). "Our results indicate that silencing of KIF3B could suppress breast cancer progression by regulating Wnt/β-catenin signaling and EMT, providing support that KIF3B could serve as a potential therapeutic target for the treatment of breast cancer." (PMID 33542902, 2020). "However, the role of KIF3B in breast cancer with Wnt signaling and the EMT process in breast cancer remains subtle." (PMID 33542902, 2020). "We found that up-regulation of KIF3B activates the Wnt signaling via increasing the expression of Dvl2, p-GSK-3βser9, total and nucleus β-catenin, then up-regulation of Wnt signaling target genes such as CyclinD1, C-myc and MMP-7, which are highly expressed in breast cancer." (PMID 33542902, 2020). "Silencing KIF3B might suppress the Wnt/β-catenin signaling pathway and EMT in breast cancer cells." (PMID 33542902, 2020). "However, the expression and related mechanisms of KIF3B in breast cancer have not been experimentally verified." (PMID 33542902, 2020). "Furthermore, we found that silencing of KIF3B decreased the expression of Dvl2, phospho-GSK-3β, total and nucleus β-catenin, then subsequent down-regulation of Wnt/β-catenin signaling target genes such as CyclinD1, C-myc, MMP-2, MMP-7 and MMP-9 in breast cancer cells." (PMID 33542902, 2020).
ciliopathy (4 papers, 2019 to 2025). A genetic disorder of the cellular cilia or the cilia anchoring structures, the basal bodies, or of ciliary function. "KIF3B encodes a kinesin motor involved in transport through the cilium and mutations in KIF3B have recently been associated with a ciliopathy that presents with RP." (PMID 33435268, 2021). "The study found that SPAG6, TRAF3IP1, IFT22, and KIF3B showed lower correlations with ciliopathies, while IFT172, TTC21B, CEP290, ACTB, and DYNC1H1 were highly correlated." (PMID 40432967, 2025).
hepatocellular carcinoma (4 papers, 2019 to 2025). A malignant tumor that arises from hepatocytes. "Increased expression of KIF3B was correlated with poor survival in patients with hepatocellular carcinoma while its inhibition decreased cancer growth and induced tumor apoptosis." (PMID 33542902, 2020). "KIF3B was overexpressed in human hepatocellular carcinoma tissues, and its downregulation might inhibit hepatocellular carcinoma proliferation." (PMID 33150178, 2020). "KIF3B has been shown to be over-expressed in multiple human cancers, such as gastric cancer, oral squamous cell carcinoma, pancreatic cancer, prostate cancer, seminoma, hepatocellular carcinoma, and acute lymphoblastic leukemia." (PMID 33542902, 2020). "For example, studies have shown that the expression of KIF3B and KIF26B is significantly increased in hepatocellular carcinoma (HCC) tissues and HCC cell lines, and the knockout of KIF3B or KIF26B stimulated apoptosis of cancer cells and reduced malignant characteristics of tumors." (PMID 40964093, 2025).
prostate carcinoma (4 papers, 2018 to 2026). A carcinoma that arises from epithelial cells of the prostate gland. "Silencing of KIF3B in an avian embryo model significantly inhibited vasculotropism and metastasis in prostate cancer cell PC3 and other cancer cells." (PMID 33542902, 2020). "Quantitative analysis of an independent prostate cancer progression TMA cohort (University of Calgary) of 98 patients showed that both Kif3b and SRPK1 display significantly higher expression levels in prostate cancer epithelium compared to benign hyperplasia epithelium." (PMID 29904055, 2018). "Both Kif3b and SRPK1 were expressed at significantly higher levels in areas where the prostate epithelium is invading into the surrounding stroma, further correlating their overexpression in the process of prostate cancer invasion and metastasis." (PMID 29904055, 2018).
colorectal cancer (3 papers, 2017 to 2021). A primary or metastatic malignant neoplasm that affects the colon or rectum. "Other genes of the locus with potential pathogenic importance in colorectal cancers, such as TPX2, KIF3B and POFUT1, are also amplified in the 12 cell lines." (PMID 34577783, 2021). "Among these, TM9SF4, POFUT1 and KIF3B are all involved in the pathway of “Colorectal cancer”." (PMID 29108255, 2017). "Over-expression of amplified genes is partially overlapping with the over-expression of the genes in 20q11.21 amplified clinical samples of colorectal cancer patients, where POFUT1 but also ASXL1, and, in fewer cases, KIF3B and TPX2, are often over-expressed." (PMID 34577783, 2021).
seminoma (3 papers, 2019 to 2022). A radiosensitive malignant germ cell tumor found in the testis (especially undescended), and extragonadal sites (anterior mediastinum and pineal gland). "KIFC1 and KIF3B are enriched in tissues of human seminoma, one of the most frequent testis cancers affecting young men, with a role in cell division regulation in seminoma." (PMID 35547823, 2022).
colon cancer (2 papers, 2018 to 2021). "In this study, KIF3B was also determined as a key factor which could visibly reverse the effects of miR-605-3p on the phenotype of the colon cancer cells." (PMID 34422048, 2021). "Therefore, the present proofs suggest that miR-605-3p blocked the progression of colon cancer via targeting KIF3B." (PMID 34422048, 2021). "Hence, this study suggests that miR-605-3p serves as a tumor inhibitor in colon cancer via suppressing the activation of Wnt/β-catenin induced by KIF3B." (PMID 34422048, 2021). "It was found that KIF3B was a target of KIF3B; decreased KIF3B could reverse the effects of miR-605-3p on colon cancer." (PMID 34422048, 2021). "Moreover, it has been also observed that the reduced KIF3B inhibited the viability and induced the apoptosis of colon cancer." (PMID 34422048, 2021).
schizophrenia (2 papers, 2020 to 2021). A major psychotic disorder characterized by abnormalities in the perception or expression of reality. "Although the presented studies concern the animal model, they are of great importance in patients with schizophrenia who were identified with KIF3B mutations." (PMID 32121669, 2020). "The kif3b mutation suppresses NMDAR containing vesicle trafficking to the spine surface membrane, resulting in a reduction in synaptic plasticity and development of schizophrenia-like symptoms." (PMID 34948207, 2021). "KIF3B plays an important role in the electrophysiological response of NMDAR and hence synaptic plasticity, which is one of the pathogenetic concepts of schizophrenia." (PMID 32121669, 2020).
Anxiety (1 paper, 2021). Intense feelings of nervousness, tension, or panic often arise in response to interpersonal stresses. "We then evaluated whether knockdown of KIF3B within the PrL produced any deleterious effect on the animals by assessing general locomotion and anxiety-like behavior." (PMID 34749771, 2021).
breast tumors (1 paper, 2020). "The results showed that KIF3B is over-expressed in primary breast tumors (n = 1097) compared to normal tissues (n = 114) (P < 0.01)." (PMID 33542902, 2020).
cervical cancer (1 paper, 2024). A primary or metastatic malignant neoplasm involving the cervix. "In conclusion, the genes PAXX and KIF3B are associated with DNA repair and cell division, supporting the GSEA study’s findings that the high-risk subgroup may affect the long-term survival of cervical cancer by influencing DNA replication and the cell cycle." (PMID 38666838, 2024).
fibrosarcoma (1 paper, 2018). A malignant mesenchymal fibroblastic neoplasm affecting the soft tissue and bone. "To confirm that this inhibitory effect is not cell type and shRNA gene knockdown technology limited we used CRISPR technology to knockout our top target, Kif3b, in the HT1080 fibrosarcoma cell line." (PMID 29904055, 2018).
Kidney Cyst (1 paper, 2026). Abnormal fluid filled sac within the kidney, either acquired or congenital. "Furthermore, it has been shown that KIF3A−/− and KIF3B−/− hPSCs lacking cilia remain pluripotent and self-renewing, but during differentiation they develop defects in neurogenesis, nephrogenesis, and kidney cyst formation." (PMID 41161866, 2026).
lymph node metastasis (1 paper, 2020). "In our study, high expression of KIF3B was shown to be associated with lymph node metastasis." (PMID 33542902, 2020). "Also, we found that the expression of KIF3B in the primary tumors with lymph node metastasis was higher than those without lymph node metastasis (P < 0.01)." (PMID 33542902, 2020).
male infertility (1 paper, 2022). The inability of the male to effect fertilization of an ovum after a specified period of unprotected intercourse. "Another member of the kinesin superfamily, KIF3B, has also been found to be mutated in some cases of male infertility." (PMID 36686457, 2022).
osteosarcoma (1 paper, 2009). A usually aggressive malignant bone-forming mesenchymal neoplasm, predominantly affecting adolescents and young adults. "The effect of knockdown of ARHGEF10, RhoA or KIF3B was also examined in osteosarcoma U2OS cells arrested in S phase by aphidicolin treatment." (PMID 19635168, 2009). "The supernumerary centrosome phenotype was also observed in S phase-arrested osteosarcoma U2OS cells when the expression of ARHGEF10, RhoA or KIF3B was abrogated by RNA interference." (PMID 19635168, 2009).
retinal dystrophies (1 paper, 2022). "The disease-associated variants for retinal dystrophies screened in this study include CEP290, KIF3B and AIPL1." (PMID 35709088, 2022).
situs inversus (1 paper, 2019). A congenital condition in which there is complete right-to-left reversal of the position of the major thoracic and abdominal organs (that is, they are arranged in a mirror image of the normal positioning). "We identified two additional lines, Kif3b and Kifap3, that showed similar profiles and have morphological phenotypes such as polydactyly and situs inversus." (PMID 31243271, 2019).